IL6 (interleukin 6)
Diseases named in the same sentence as IL6 in open-access papers (continued):
Sharing a sentence is not in itself a finding about the gene and the disease.
infection (continued). "The present study demonstrates the existence of a characteristic relationship between neutralizing activity against Omicron, IL-6 levels, and cTfh proportions in Omicron breakthrough infection." (PMID 38694512, 2024). "On the contrary, we found that the ECRG4 KO mouse infection had increased expression of IL1β (P = 0.0053), IL-6 (P = 0.047) and TNFα (P = 0.024), with a trend towards increased CXCL1." (PMID 39509414, 2024). "Direct infection of the atherosclerotic plaque by SARS-CoV-2 produces an enhanced inflammatory response with the release of cytokines such as IL-6 and IL-1β, which are key to the formation of a plaque." (PMID 38541641, 2024). "Of all the cytokines involved, interferon-alpha (IFN-α), interleukin-1α (IL-1α) and interleukin-6 (IL-6) are of particular interest in this type of infection." (PMID 39772252, 2024). "As expected, gnotobiotic chicks with S. Typhimurium infection showed multiple fold increase in the expression levels of various pro-inflammatory cytokines and chemokines; IL-18, IL-1β, IL-6, and IL-8L1 at day 5 post-infection." (PMID 38315031, 2024). "IL-6 is a pleiotropic cytokine secreted upon infection, and elevation is usually seen in S. pneumonia infection." (PMID 39108408, 2024). "For decades, interleukin 6 (IL‐6), procalcitonin (PCT), and C‐reactive protein (CRP) have been widely investigated to identify pathogenic bacteria, evaluate the severity of infection, and predict adverse outcomes in cancer patients." (PMID 38967137, 2024). "We found that expression of NF-κB target genes TNF-α, IFN-γ, IL-6 and IL-8 were modulated during the course of infection." (PMID 39325775, 2024). "Overall, these results suggest that TNF is crucial for inducing chemokine and IL-6 production during craniotomy infection, specifically in the galeal compartment, aligning with previous reports." (PMID 39044282, 2024). "In DLD-1 cells, the expression of IL-1β and IL-8 were upregulated while TNF-α and IL-6 expression were downregulated after LV infection." (PMID 39427065, 2024). "As M. tuberculosis infection causes chronic inflammation, infected mice showed increased TNF-α and IL-6 levels in the lung after 52 weeks of infection." (PMID 38958367, 2024). "Noteworthy, similar to the previous analyses, the profile of IL-6 and IL-10 cytokines show the greatest changes during infection, especially when the infection occurs in the 1st gestational trimester." (PMID 39495782, 2024). "IL-6 is a multifunctional cytokine that is primarily responsible for mediating the acute-phase response, an innate immune mechanism activated by infection and inflammation." (PMID 39195835, 2024). "The use of serum biomarkers, such as IL-6, C-reactive protein, ferritin, d-dimer, white blood cell count, and lymphocyte count, is crucial for staging the infection." (PMID 39540054, 2024). "We also did not observe a dramatic difference in immune response between infection with wild-type V587 and the ΔhylAΔhylB strain, other than a slight reduction in IL-6 in the bladders of mice infected with ΔhylAΔhylB at 6 hpi." (PMID 38842305, 2024). "Interleukin-6 (IL-6) is an important proinflammatory cytokine that is released during infection or tissue injury and promotes innate and acquired immune responses." (PMID 38424624, 2024). "The IL-6 levels increase significantly in severe infection, and its continuous rise often indicates a poor prognosis." (PMID 39411281, 2024). "It is known that enhancements in serum concentrations of IL-6 and sIL-6R during infection lead to an increased agonistic trans-signalling mechanism." (PMID 39063569, 2024). "Interleukin-6 (IL-6) is a cytokine produced immediately and in large quantities during tissue injuries as well as infection; it induces acute phase response mechanisms, immune reactivity, and hematopoiesis." (PMID 39683624, 2024). "We show that the loss of STING results in higher bacterial loads and abrogates IFNβ and IL6 induction at 12 days post-infection." (PMID 38459007, 2024).
infection (continued). "Supernatant of THP-1 macrophages was collected following 24 or 48 hours of MAP infection and used in two separate ELISAs to determine the concentration of IL-6 and sIL-6R." (PMID 39170608, 2024). "Consistently, quantitative PCR analysis revealed that the mRNA expression of inflammatory cytokines, including IFN-γ, IL-6, and TNF-α, was upregulated in the lungs of MA10-infected mice, suggesting that MA10 infection caused lung injury." (PMID 38634132, 2024). "IL-6, being a pleiotropic cytokine, predominantly participates in early inflammatory processes and attains peak expression during the initial phases of infection." (PMID 38698289, 2024). "IL-6 plays a pivotal role in the immune response to infection, and it is released by various cells, including macrophages and T cells, in response to inflammatory stimuli." (PMID 39835102, 2024). "There was a critical increase in the level of IL-6 expression in response to infection with L. europaeus, genotype GI.2 (261-fold change), and much smaller in the GI.1 group (8.5-fold change)." (PMID 39273479, 2024). "The rapid production of IL-6 contributes in host defense during tissue injury and infection, whereas excessive production and accumulation of IL-6 often lead to disease pathology." (PMID 39125464, 2024). "This is consistent with observations that IL-6 is immediately synthesized in response to infection, activating an acute immune response and inducing CRP production by hepatocytes." (PMID 38709460, 2024). "In contrast, rapid IL-6 synthesis which is a powerful acute phase response inducer aids in host defense during infection and tissue damage, however overproduction of IL-6 is a factor in a disease pathology." (PMID 38643105, 2024). "This literature indicated that IL-1β and IL-6 are mediating host protection against parasites infection, activating and inflammatory responses." (PMID 39749330, 2024). "IL-1β and IL-6 are pro-inflammatory cytokines that are crucial for host-defense responses to infection and injury." (PMID 38464701, 2024). "Interleukins are the most important cytokines released during infection, which include IL-1β, IL-18, IL-6, IL-12, and IL-17." (PMID 39042701, 2024). "We observed that ST-challenged neonatal broilers after 24 h post-infection had significant increases in pro-inflammatory cytokines- IL-6 (p = 0.0025), IL-16 (p = 0.0196), and IL-21 (p = 0.0066)." (PMID 38465263, 2024). "At 24 h post infection in 31 human lung explant tissue samples, key cytokines such as interleukin (IL)-6, IL-10, tumor necrosis factor-alpha (TNF-α), and interferon-gamma (IFN-γ) were upregulated." (PMID 39456722, 2024). "Following infection with both viruses, increased levels of IL-12, IL-6, IFN-α and IL-1RA were found between 3–7 dpi." (PMID 39186783, 2024). "Eight hours after M. gallisepticum infection in chicken primary alveolar type II epithelial cells, large amounts of TNF-α and IL-6 were produced and inflammation was suppressed 24 h after infection." (PMID 38474071, 2024). "As a pleiotropic cytokine, IL-6 is primarily produced in response to stress and infection in the presence of inflammatory stimuli." (PMID 38881895, 2024). "The gene expression levels of four cytokines; TNF-α, IL-6, IL-1β, and IL-8 were tested in the cell lines after infection." (PMID 39427065, 2024). "Fibroblasts within the peritoneal cavity are also capable of producing IL-6 upon activation, as are neutrophils in the setting of early response to inflammation or infection." (PMID 38689325, 2024). "TNF-α, IL-1β and IL-6 are all pro-inflammatory cytokines, and they play complex roles in the inflammatory response, that can both help the host defend against infection and promote inflammation." (PMID 39176281, 2024). "The infection of macaques with HTLV-1WT or HTLV-1p12KO was associated with higher plasma levels of IL-10 after 21 weeks, while IL-6, IFN-γ, IL-18, and IL-1β were only elevated in animals infected with HTLV-1WT." (PMID 38668247, 2024).
infection (continued). "Infection with T. gondii increased the production of all other cytokines (IL-6, IFN-γ, TNF, IL-10, and IL-17A) in all experimental groups." (PMID 39417497, 2024). "We found that levels of IL-6 at 24 hours after infection was significantly lower in the lungs of mice treated with CETPi compared with control, whereas levels of IL-1β and TNF-α were unchanged." (PMID 38646937, 2024). "Following a six-hour post-infection period, the IL-6 and TNF-α levels in mouse serum were quantified." (PMID 38912723, 2024). "IL-6, promptly and transiently produced in response to infections and tissue injuries, contributes to host defense through the stimulation of acute phase responses, hematopoiesis, and immune reactions." (PMID 38474155, 2024). "IL-6 is released in inflammatory states by WBCs and urothelial cells, with a wide range of functions, presenting an important part in the anti-infection immune responses." (PMID 39766247, 2024). "Overall, our findings indicate that exogenous administration of IL-6 during early (3-dpi) systemic infection increases fungal burden in lungs, blood, and brain." (PMID 39334365, 2024). "The nisin treatment groups had lower cytokine expression levels (TNF-α and IL-6) in the oral cavity and uterus compared to the infection groups." (PMID 39203489, 2024). "IL-6 level on day 4 of febrile neutropenia was significantly higher in the episodes with a microbiologically documented infection." (PMID 38672594, 2024). "These immune cells are known to produce IL-10, particularly during the resolution phase of the infection, and also IL-6 and IL-27, which promote the maturation of Treg cells in the respiratory tract." (PMID 39595633, 2024). "In a study of CD-19 CART for relapsed refractory B-cell lymphoma, patients who developed severe infections had elevated IL-6 levels on the day of the event compared with the CRS-only cohort (median 2243 pg/mL versus 64 pg/mL, P = 0.03)." (PMID 39559703, 2024). "The IL-6 level of the mixed bacteria was highest and showed a different trend from non-infection, and the quarter was infected with streptococcal bacteria." (PMID 39195804, 2024). "Cytokines are pivotal mediators of immune responses, and the host can stimulate the production of Th1 and Th2 cytokines, such as IL-4, IL-5, IL-6, IL-10, and IL-13, to combat infections." (PMID 38786064, 2024). "In this study, coumarin derivative supplementation in C. rodentium-infected mice downregulated the cytokine genes for IL-6 and IL-1b, which were increased by infection in colonic tissues." (PMID 39081865, 2024). "It seems most likely to us that elevated IL-6 levels indicate the occurrence of infection, and that infection promotes the development of POD." (PMID 39112758, 2024). "In contrast, IL-6 levels were significantly elevated in colon tissues from mice treated for translocated infection, while IL-10 expression remained unchanged across all groups." (PMID 39664059, 2024). "Previous studies have reported the presence of IL-6 during the active phases of infection by several Leishmania species." (PMID 38359037, 2024). "TNF‐α and IL‐6 are pro‐inflammatory cytokines that play pivotal roles in the immune response and are often used as markers of inflammation and infection." (PMID 39422648, 2024). "Patients with IL-6 levels lower than 84.00 pg/mL on POD 3 can ensure safe early discharge with a low probability of infections." (PMID 38504206, 2024). "The most pronounced effect was observed for the mRNA levels of Il-6, which peaked on day 7 post-infection with a 40-fold increase relative to mock-infected mice." (PMID 39338937, 2024). "According to these notions, we find lower IL-6 levels in individuals with infection and vaccination." (PMID 38474155, 2024). "Of interest, IFN-γ, IL-1β and IL-6 lung cytokine levels were significantly increased in the lung at both two- and three-weeks post-infection." (PMID 38198478, 2024).
infection (continued). "Interleukin-6 (IL-6) is a cytokine responsible for inflammation and plays a vital role in the immune response to stress, including the onset of infection." (PMID 39416746, 2024). "The key finding is that IL-6 and IL-10 levels rise earlier in secondary infections compared to primary infections, whereas elevated cytokine levels typically occur later in the febrile phase." (PMID 39457019, 2024). "At the same time, there is a predominance of the IL-6/IL-10 ratio, which likely indicates the severity of the infection." (PMID 38397914, 2024). "After 7 days of infection, the levels of Th1 cytokines IFNγ, IL-6, and TNFα were elevated in the BALF, but these levels were significantly reduced in TLR7 KO mice." (PMID 39769461, 2024). "Our findings suggest that IL-6 production by microglia, although marginally, enhances cryptococcal phagocytosis, which is important for infection control especially upon brain penetration." (PMID 39334365, 2024). "A detailed temporal analysis of the pro-inflammatory cytokines secreted by human PBMCs showed an increased concentration of IL-1β, IL-6 and TNFα starting at 4 h post-infection, with IFNγ amounts rising at 8 h post-infection." (PMID 38793740, 2024). "Both DV1-5P7Sp and DV3P12/08P4Bm infections increased IL-6 mRNA in the liver (8.9 × 10 or 1.4-fold) and small intestine (2.8 × 102 or 4.5× 10-fold)." (PMID 38550855, 2024). "Studies have shown a positive regulation of the gene expression of pro-inflammatory cytokines (IL-1β, TNF-α, and IL-6) in human macrophages after infection with L. amazonensis and L. major." (PMID 39199338, 2024). "Beta P20 infection was associated with greater inflammatory cytokine production (CCL2, CXCL1, IL-6) than P0 (p < 0.005, p = 0.051, p < 0.05, respectively)." (PMID 38365933, 2024). "Interleukin-6 (IL-6) is an important cytokine in adaptive immune responses, as well as in infection, autoimmune disorders, cardiovascular diseases, and certain cancers." (PMID 38914713, 2024). "Infection or CNS damage can activate microglia, and activated microglia release IL-6, IL-1β, and TNF-α." (PMID 39661619, 2024). "NO is a central mediator of pathogenesis in infection, while IL-6 is a pro-inflammatory cytokine that results in the occurrence of rapid and transient tissue damage in response to infection." (PMID 39200075, 2024). "IL-1β and IL-6 are pro-inflammatory markers that play crucial roles in promoting inflammation and facilitating the recruitment and activation of immune cells at infection sites." (PMID 39595561, 2024). "Trends for P80-mediated drop in inflammatory processes during infection were further visible for IL-6 and IL-1α (pink and yellow bar charts), though these were not significant." (PMID 38419061, 2024). "Conditions of infection and inflammation, specifically high levels of IL-6, tend to increase the expression of hepcidin, which then degrades FPN1." (PMID 38641847, 2024). "A more rapid response to DD infection for IL-6 was only found for chronic (M4) and focal flare-ups (M4.1) of DD (p = 0.006)." (PMID 39595313, 2024). "Increased transcription of collagen triple-helix repeat complex (cthrc) and alpha smooth muscle actin (α-sma) suggested the participation of activated fibroblasts in ΔadsA infection as did the combination of increased IP-10, IL-6, MCP-1 and TGFB1 29,30." (PMID 39134708, 2024). "We conducted a comprehensive assessment of the diagnostic potential of CRS, fever, PCT, IL-6, and CRP for the early detection of severe infection in febrile patients following CTI." (PMID 38956649, 2024). "Regarding IL6, which is a pleiotropic cytokine produced by various cell types in the context of infection, inflammation, and malignancy, our findings were in line with other works that found elevated IL6 levels in the serum of SpA patients." (PMID 38449853, 2024).
infection (continued). "L. major rapidly stimulates keratinocytes, which in response produce immunomodulatory factors (IL-12, IL-1β, osteopontin, IL-4 and IL-6) that influence the progression of the infection." (PMID 39691716, 2024). "In peritoneal macrophages upon SIRT1 (EX-527-1 μM) or SIRT3 (3-TYP-1μM) chemical inhibitor treatment, an increase in IL-6 and IL-1β cytokine levels was observed at 6 hr post-infection." (PMID 39693143, 2024). "Five studies demonstrated higher systemic levels of IL-6, which integrates the immune defense against infections, in individuals with Sh infection versus individuals without Sh infection." (PMID 39250522, 2024). "The results showed that on the 12th day after infection, IL-1β and IL-6 were still highly expressed in the untreated group and the RBDA group, suggesting a strong inflammatory response because the wound was still infected." (PMID 38970013, 2024). "The inflammatory cascade triggered by injury, infection, or tissue damage is a complex process that led to the stimulation of the immune system and the release of key modulators such as nitric oxide (NO) interleukin 6 (IL-6), and tumor necrosis alpha (TNF-α)." (PMID 39061039, 2024). "Using qPCR, we evaluated the expression of cytokines that are important for neutrophil recruitment to sites of infection, including IL1β, IL-6 and TNFα, as well as the neutrophil chemokines CXCL1 and CXCL2." (PMID 39509414, 2024). "The IL-6 has previously been shown to be important for host resistance to F. tularensis LVS infection." (PMID 38533334, 2024). "During the infection an important increase of cytokines like IL-6, interferon γ (IFN-γ) and Tumor Necrosis Factor alpha (TNF α) had been documented." (PMID 37500944, 2024). "After 6 hours of infection, we measured the expression levels of the proinflammatory cytokines IL-6 and TNF-α." (PMID 38912723, 2024). "High levels of TNF-α, IL-1β and IL-6 and MDA in the SE-stimulated mice indicated that SE infection caused an imbalance in the redox status, resulting in oxidative stress and inflammatory responses." (PMID 39456517, 2024). "IL‐6 is a pro‐inflammatory cytokine mostly secreted by T‐cells to stimulate the immune response during infection and tissue damage." (PMID 39632267, 2024). "A distinct cytokine profile (severe elevation in interferon-γ and IL-10 with a modest elevation in IL-6) in children helps differentiate HLH from infection." (PMID 39398688, 2024). "The primary infection primed monocytes and mDCs for an increased IL-6 and TNF-α production after restimulation with E. coli or TLR ligands ex vivo." (PMID 38474721, 2024). "Research in mice has shown that IAV subtype H1N1 infection elevated the apoptosis rate in neutrophils within the lung, whereas the proinflammatory cytokine, IL-6, counteracted this effect, promoting cell survival." (PMID 38256213, 2024). "IL-6 on POD 3 predicted infection with an AUC of 0.84, the cutoff value of 84.00 pg/mL, a sensitivity of 85.70%, and a specificity of 82.70%, PPV of 36.00%, and NPV of 98.10%." (PMID 38504206, 2024). "Post-infection, excessive production of inflammatory mediators such as IL-1β, IL-6, IL-8, TNF-α, MCP-1, and IP-10, as well as the presence of endothelial inflammation markers (IL-6, TNF-α, ICAM-1) in lung tissues, have also been reported." (PMID 38600563, 2024). "IL-2R, IL-6, IL-8, and IL-10 were significantly higher in severely ill patients from week 1 to week 5 post infection." (PMID 38641847, 2024). "Of all the cytokines involved, interferon-alpha (IFN-α), interleukin 1 alpha (IL-1 α) and interleukin-6 (IL-6) are of particular interest in this type of infection." (PMID 39772252, 2024). "Cytokines tend to be markedly elevated, particularly IL-6 and IL-10, following co-infections in hematologic neoplasms, which has implications for predicting early infections and differentiating between G- from G+." (PMID 39559703, 2024).